ALK (ALK receptor tyrosine kinase)
Diseases named in the same sentence as ALK in open-access papers (continued):
Sharing a sentence is not in itself a finding about the gene and the disease.
uterine carcinosarcoma (4 papers, 2017 to 2023). A usually aggressive malignant neoplasm arising from the uterine corpus and less often the cervix. "A previous study suggested that in uterine carcinosarcomas, the ALK-mediated Akt/NF-κB/Twist1 pathway participates during the initial stage and regulates morphological alterations towards the sarcomatous phenotype." (PMID 36425467, 2022). "Recently, the deregulated expression of full-length ALK has been observed in some primary solid tumors, but little is known about its involvement in the tumorigenesis of uterine carcinosarcomas (UCSs)." (PMID 28193280, 2017). "Previous studies reported a role for ALK in the inhibition of apoptosis in uterine carcinosarcoma." (PMID 35351152, 2022). "ALK induces CSC features through activation of the epithelial-mesenchymal transition (EMT) in ovarian high-grade serous carcinomas and uterine carcinosarcoma." (PMID 37592266, 2023).
Uterine tumor (4 papers, 2015 to 2025). "In general, uterine tumors that are positive for ALK protein or harbor ALK gene rearrangements should preferentially raise suspicion for IMT." (PMID 41179654, 2025). "If an IMT is in the differential diagnosis for a uterine neoplasm, CGP can identify genomic rearrangements of non-ALK kinases, which will strongly support the diagnosis of an IMT as seen in IMT of soft tissue." (PMID 26062823, 2015).
venous thromboembolism (4 papers, 2017 to 2026). Occlusion of the lumen of a vein by a thrombus that has migrated from a distal site via the blood stream. "Accumulating evidence links the echinoderm microtubule-associated protein-like 4 (EML4)-anaplastic lymphoma kinase (ALK) rearrangement to venous thromboembolism (VTE) in non-small cell lung cancer (NSCLC) patients." (PMID 37940761, 2024). "Conversely, ALK-positive NSCLC is associated with a high rate of venous thromboembolism." (PMID 34943412, 2021).
adenocarcinoma in situ (3 papers, 2012 to 2016). A lesion in which the normally situated glands are partially or completely replaced by atypical cells with malignant characteristics. "However, in our case, the adenocarcinoma in situ of the left lung was immunohistochemically negative for ALK." (PMID 23617234, 2013).
alveolar soft part sarcoma (3 papers, 2023). An alveolar soft part sarcoma occurring in adults. "This is the case of ALK inhibitors such as crizotinib for inflammatory myofibroblastic tumors, antiangiogenics for the treatment of alveolar soft-part sarcoma (ASPS), crizotinib for clear-cell sarcomas, CSF-1R inhibitors in tenosynovial giant cell tumors or mTOR inhibitors in PEComa." (PMID 37958362, 2023). "Following this observation, the drug was also reported to be active in ALK-positive IMT, MET-positive alveolar soft part sarcoma, and MET-positive clear-cell sarcoma, in the biomarker-driven phase 2 EORTC 90101 CREATE trial." (PMID 37998367, 2023). "Several oral tyrosine–kinase inhibitors (TKI) have also demonstrated activity for STS, including multi-TKI pazopanib for non-adipocytic STS, anaplastic lymphoma kinase (ALK) inhibitors for myofibroblastic tumors with ALK fusions, and cediranib for alveolar soft part sarcoma (ASPS)." (PMID 37190214, 2023).
Arrhythmia (3 papers, 2015 to 2023). Any cardiac rhythm other than the normal sinus rhythm. "Arrhythmia was a common adverse drug reaction of ALK-TKIs in recent studies, mainly including bradycardia, QT prolongation, and atrioventricular (AV) block, and most of them were assessed as less than or equal to grade 2, but rare serious AEs still possibly exist." (PMID 35370632, 2022). "The partial reduction in ALK function throughout development did not cause arrhythmia nor did it suppress arrhythmia in Nf1P1/P2 flies." (PMID 26536237, 2015). "At present, there is no consensus on the pathogenesis of ALK inhibitor‐related arrhythmia, and plausible mechanisms that involve ion signaling pathways, endocrine regulation, and drug metabolism may underlie this condition." (PMID 36535917, 2023).
benign fibrous histiocytoma (3 papers, 2021 to 2025). A benign neoplasm composed of fibroblastic spindle cells in a whorled storiform pattern. "Based on the unusual morphology for benign fibrous histiocytoma, the ALK expression by IHC and the fact that “epithelioid fibrous histiocytoma (EFH)” commonly demonstrate ALK fusions, NGS testing was performed and revealed IRF2BP2-NTRK1 fusion." (PMID 32860002, 2021). "Benign fibrous histiocytomas show storiform pattern and on immunohistochemistry they are negative for ALK." (PMID 41268585, 2025).
bone cancer (3 papers, 2014 to 2022). A primary or metastatic malignant neoplasm affecting the bone or articular cartilage. "The disease named as “tumourigenesis of bone tumour” was associated to small indel in ALK gene and was present only in the tumour tissue." (PMID 25496518, 2014). "For example, only one positively selected gene was detected in bone cancer (IDH1) and nervous system cancer (ALK), respectively." (PMID 28938601, 2017).
chordoma (3 papers, 2021 to 2025). Chordomas are rare malignant tumors arising from embryonic remnants of the notochord in axial skeleton. "The ALK/MET inhibitor crizotinib affects sacral chordoma cell growth and cMET phosphorylation, making it a potential therapeutic candidate." (PMID 41442054, 2025). "Furthermore, a screening of 133 approved cancer drugs, which included tyrosine kinase inhibitors, HDAC inhibitors, and proteasome inhibitors, the ALK/MET inhibitor crizotinib demonstrated promising potential for standard chemotherapy regimens for chordomas." (PMID 41442054, 2025). "The ALK/MET inhibitor crizotinib, as a potential therapeutic agent for chordomas, led to a reduction of proliferation markers and the modulation of key DNA repair and cell cycle regulatory genes, with CDC20 and FOXO4 playing a pivotal role." (PMID 41442054, 2025). "For example, ALK/MET inhibitors affected the growth behaviour and cMET phosphorylation state of chordoma cells in different ways and works more efficiently in sacral cells than in clival cells." (PMID 41442054, 2025). "The ALK/MET inhibitor crizotinib, considered a potential treatment for chordomas, reduced proliferation markers and modulated important genes related to DNA repair and cell cycle regulation, with CDC20 and FOXO4 being particularly significant." (PMID 41442054, 2025).
colorectal tumors (3 papers, 2021 to 2023). "Interestingly, an ALK-fusion gene was detected among one of the colorectal tumors in our study." (PMID 35648382, 2023). "There were no instances of MSI in 56 non-colorectal tumors carrying ALK, ROS1, RET or NTRK1 rearrangements." (PMID 37686416, 2023).
depression (3 papers, 2017 to 2021). "US9126931B2 relates to tetracyclic compounds as ALK inhibitors for treating a disease accompanied by an abnormality in ALK, for example, cancer, depression, and cognitive function disorder." (PMID 34451807, 2021). "Brain metastases are common with ALK+ NSCLC substantiating patients' symptoms (fatigue, headaches and depression), treatment cost, outpatient visits and inpatient stays." (PMID 30687633, 2018).
desmoid fibromatosis (3 papers, 2015 to 2024). "The diagnostic value of ALK-1 positivity is evident, considering most of the neoplastic counterparts of IMTs including desmoid fibromatosis, nodular fasciitis, calcifying fibrous tumor, myofibromatosis, and infantile fibrosarcoma are negative for ALK." (PMID 25763286, 2015).
emphysema (3 papers, 2021 to 2022). "In this study, compared with non‐ALK&ROS1/EGFR mutations in NSCLC patients, patients with EGFR mutation had a lower incidence of pulmonary emphysema." (PMID 35081265, 2022). "In the ALK&ROS1‐positive group, the most were female (χ2 = 7.644, P = 0.008) patients, and proportion of patients with emphysema was lower (χ2 = 8.202, P = 0.003) than the ALK&ROS1‐negative group." (PMID 35081265, 2022).
end-stage renal disease (3 papers, 2019 to 2025). "According to FAERS analysis, ALK inhibitors can cause acute or chronic renal insufficiency and may also cause electrolyte abnormalities such as hyponatremia and hypophosphatemia." (PMID 39026680, 2024).
Fanconi anemia (3 papers, 2019 to 2023). Fanconi anemia (FA) is a hereditary DNA repair disorder characterized by progressive pancytopenia with bone marrow failure, variable congenital malformations and predisposition to develop hematological or solid tumors. "Pathway analysis revealed four pathway clusters: Hop pathway in cardiac development, ALK in cardiac myocytes, leukocyte transendothelial migration and Fanconi Anemia pathway." (PMID 38110438, 2023). "The same authors further treated a child with ALK-I1171T high-risk NB that was not responding to conventional treatment due to an underlying congenital genetic condition, Fanconi anemia." (PMID 36839989, 2023).
fibromatosis (3 papers, 2015 to 2025). A poorly circumscribed neoplasm arising from the soft tissues. "Similarly, fibromatosis also lacks ALK expression and is commonly associated with abnormal nuclear accumulation of β-catenin due to mutations in the CTNNB1 gene." (PMID 41179654, 2025).
hypogonadism (3 papers, 2015 to 2024). A disorder characterized by decreased function of the gonads. "The patient was reluctant to start on ALK inhibitor due to potential side-effect of hypogonadism." (PMID 38594735, 2024).
hypothyroidism (3 papers, 2019 to 2024). Abnormally low levels of thyroid hormone. "Therefore, clinicians should be aware that hypothyroidism may lead to bradycardia and regular monitoring of thyroid function in patients taking ALK inhibitors is necessary." (PMID 36535917, 2023).
lymphangitis (3 papers, 2016 to 2024). Inflammation of the lymphatic vessels. "In this study, we found that EGFR mutations were associated with GGO, KRAS mutations were associated with solid tumors that had low tendencies to metastasize to the lung and pleura, and ALK rearrangements were associated with lymph node involvement and lymphangitis." (PMID 27518729, 2016). "Lymphangitis was significantly more common among ALK-positive patients, compared to EGFR-positive patients (p = 0.049)." (PMID 27518729, 2016). "ALK-positive patients were significantly more likely to have more lymphangitis, compared to EGFR-positive patients (p = 0.049)." (PMID 27518729, 2016).
neuronal tumor (3 papers, 2018 to 2024). Neuronal brain tumors are an uncommon group of central nervous system tumors that arise from cells with neuronal differentiation. "TAFA1, ALK, and VAV3 were some of the topmost DE genes in glioneuronal/neuronal tumors." (PMID 36865335, 2023).
nodular fasciitis (3 papers, 2019 to 2023). A self-limiting, rapidly growing, non-encapsulated benign neoplasm that arises from the soft tissues. "However, the diagnosis of nodular fasciitis can be excluded when ALK staining is positive." (PMID 37735390, 2023).
pancreatic adenocarcinoma (3 papers, 2022 to 2025). "NVP-TAE684 is an anaplastic lymphoma kinase (ALK) inhibitor that inhibits the proliferation of human pancreatic adenocarcinoma cells." (PMID 35249533, 2022).
PEComas (3 papers, 2022 to 2025). "PEComas with TSC1/2 mutations or TFE3 rearrangements respond to mTORC1 inhibition, while IMTs harboring ALK, RET, PDGFRB, or NTRK rearrangements demonstrate marked responses to ALK or TRK inhibitors." (PMID 41463261, 2025). "In general, fusion-driven neoplasms, including JAZF1-rearranged LG-ESS, YWHAE- or BCOR-altered HG-ESS, ALK- or NTRK-rearranged IMTs, and TFE3-rearranged PEComas, harbor early, lineage-defining genomic events that are consistently detectable across disease stages." (PMID 41463261, 2025).
pericarditis (3 papers, 2024 to 2025). An inflammatory process affecting the pericardium. "In conclusion, the most frequently observed adverse cardiac effects associated with ALK inhibitors are arrhythmia and pericarditis." (PMID 40346640, 2025). "Pericarditis is a frequently observed primary side effect in cancer patients undergoing treated with ALK inhibitors." (PMID 40346640, 2025). "For example, all five approved ALK inhibitors exhibited significantly elevated RORs for pericarditis in VigiBase." (PMID 40828781, 2025). "Age-stratified analysis showed significant signals in the younger patients group for endocardial disorders with ponatinib (BCR-ABL) and pericarditis with brigatinib (ALK), with no reports in the older patients group." (PMID 39687301, 2024).
prostate small cell carcinoma (3 papers, 2018 to 2022). A neuroendocrine carcinoma of the prostate gland with unfavorable prognosis, composed of small cells containing neurosecretory granules. "In support of this, a recent case report demonstrated efficacy of the ALK inhibitor alectinib in a de novo prostatic small-cell carcinoma harboring a p.F1174C ALK mutation." (PMID 36337169, 2022). "The ctDNA assay for the determination of the anaplastic lymphoma kinase (ALK) gene mutation (ALK F1174C) in small cell carcinoma of the prostate, establishes a molecular profile that could focus the treatment on the use with ALK inhibitor (alectinib)." (PMID 32629823, 2020).
pulmonary hypertension (3 papers, 2020 to 2024). Increased pressure within the pulmonary circulation due to lung or heart disorder. "For example, cardiotoxicity caused by ALK, ROS1, EGFR-TKIs; aortic coarctation caused by VEGF-TKI; pulmonary hypertension caused by ALK-TKI, interstitial pneumonia caused by EGFR/ALK TKIs, infection caused by BTK inhibitors and other adverse reactions." (PMID 36761953, 2023). "Further trials are needed to confirm whether targeting the ALK pathway can reverse PH; present data indicate that inhibition of the activin receptor-like kinase pathway might result in slight reversal ([S]-crizotinib, IN-1233, K02288) or even progression ([R]-crizotinib) of pulmonary hypertension." (PMID 39684570, 2024). "A pharmacovigilance analysis of ALK-TKI inhibitors conducted through the FDA Adverse Event Reporting System (FAERS) identified several important safety signals, including pulmonary arterial hypertension, rectal perforation, myasthenia gravis, and photosensitivity." (PMID 36761953, 2023). "However, the role of the TGF-β/ALK pathway in the pathogenesis of pulmonary hypertension is not clearly defined." (PMID 32566097, 2020).
rectal adenocarcinoma (3 papers, 2014 to 2018). "One rectal adenocarcinoma patient (0.6%) showed intense, granular staining (3+) by ALK IHC." (PMID 26172300, 2015).
rectal cancer (3 papers, 2015 to 2025). A primary or metastatic malignant neoplasm that affects the rectum. "NTRK alterations (NTRK1/2/3) were present in 0.9% and 0.5%, ROS1 alterations in 0.4% and 0.2%, RET alterations in 0.6% and 0.4%, and ALK alterations in 0.5% and 0.4% of samples in colon and rectal cancer, respectively." (PMID 39865537, 2025). "One ALK fusion gene was found in rectal cancer, with SMEK2 as a novel fusion partner." (PMID 26678488, 2015). "Fusions appeared to be more common in colo-rectal cancers with RET (CCDC6-RET), ALK (EMl4-ALK) and multiple fusions (RAF1, BRAF, and FGFR3) than in NSCLC patients, but larger studies are necessary to confirm this tendency." (PMID 35267628, 2022).
Renal insufficiency (3 papers, 2016 to 2021). A reduction in the level of performance of the kidneys in areas of function comprising the concentration of urine, removal of wastes, the maintenance of electrolyte balance, homeostasis of blood pressure, and calcium metabolism. "One patient (case #5) did not receive ALK TKI due to renal insufficiency, a known contraindication." (PMID 32674491, 2020).
respiratory failure (3 papers, 2020 to 2024). The significant impairment of gas exchange within the lungs resulting in hypoxia, hypercarbia, or both, to the extent that organ tissue perfusion is severely compromised. "Till now, there is only one documented case in the literature of mediastinal EIMS with ALK fusion reported, where unfortunately, the patient experienced rapid disease progression and succumbed to respiratory failure just 1 day before receiving a formal diagnosis." (PMID 39144623, 2024).
signet ring cell adenocarcinoma (3 papers, 2017 to 2022). "For example, a study showed 2.3% positive cases of ALK translocation by FISH using the standard criteria of at least 15% positive cells for the break-apart signal in signet ring cell carcinoma of the gastrointestinal tract." (PMID 36145589, 2022).
thoracic tumors (3 papers, 2023 to 2025). "Before and after PSM, factors associated with better OS through multivariable analysis were that thoracic tumor radiotherapy, radiotherapy, N0‐2, and ALK‐TKIs." (PMID 37288833, 2023). "Multivariate analysis revealed that thoracic tumor radiotherapy, radiotherapy, T1‐2, N0‐2, and ALK‐TKIs were independent predictors of better OS." (PMID 37288833, 2023). "Univariate analysis showed that T1‐2 stage, N0‐2 stage, MPE only, No brain metastases, No liver metastases, Involving organ ≤3, ALK‐TKIs, radiotherapy, and thoracic tumor radiotherapy were significantly related with more excellent OS." (PMID 37288833, 2023).
Thrombocytopenia (3 papers, 2021 to 2025). A reduction in the number of circulating thrombocytes. "ALK+ ALCL with low CD25 expression is associated with older patient age and increased frequency of thrombocytopenia and surface CD3 and CD8 expression." (PMID 40507248, 2025). "Compared to patients with CD25-high ALK+ ALCL, CD25-low patients were older (40 vs. 29 years, p = 0.01) and more frequently had thrombocytopenia (40% vs. 0%, p = 0.02)." (PMID 40507248, 2025). "The ALK+ ALCL patients with low CD25 expressions were often older and more frequently had thrombocytopenia and surface CD3 and CD8 expression." (PMID 40507248, 2025). "Compared with ALK+ ALCL patients with CD25-high neoplasms, patients with CD25-low neoplasms were older (median: 40 years vs. 29 years, p = 0.01) and more often had thrombocytopenia (40% vs. 0%, p = 0.02)." (PMID 40507248, 2025). "Low CD25 expression identified non-typical ALK+ ALCL cases characterized by older age, thrombocytopenia, and increased surface CD3 and CD8 expression." (PMID 40507248, 2025). "Compared with the non-leukemic ALK-negative ALCL group, patients with leukemic disease more often had absolute lymphocytosis (50% vs. 0%, p = 0.008), thrombocytopenia (60% vs. 11%, p = 0.03), bone marrow involvement (50% vs. 14%, p = 0.04), and CD7 positivity (71% vs. 19%, p = 0.02)." (PMID 34944936, 2021). "The clinical features of the patients with leukemic ALK-negative ALCL in this study were similar to the patients with non-leukemic disease, except that the patients with leukemic disease had a higher frequency of bone marrow involvement, absolute lymphocytosis, and thrombocytopenia." (PMID 34944936, 2021).